OXTR (oxytocin receptor)
Diseases named in the same sentence as OXTR in open-access papers (continued):
Sharing a sentence is not in itself a finding about the gene and the disease.
psychotic disorder (7 papers, 2015 to 2025). An abnormal condition of the mind that involves a loss of contact with reality. "Although normal peripheral OT levels have been reported in psychotic patients, several SNPs in the OXTR gene are associated with psychosis, supporting the hypothesis that the OT system is affected at the receptor level." (PMID 35688807, 2022). "First, our results showed increased OXT and OXTR in the placentas of women who underwent a first episode of psychosis during pregnancy." (PMID 37373400, 2023). "Recent studies have pointed out altered methylation patterns of the oxytocin receptor gene (OXTR) in various psychiatric disorders, including psychosis." (PMID 35688807, 2022). "The second referenced study also has important differences with our study: their patients were diagnosed with psychotic disorders (total of 242) and again a different region within the OXTR promotor was analyzed." (PMID 35672748, 2022). "Our findings indicate that while oxytocin pathway genes do not appear to contribute to the susceptibility to psychotic disorders, variations in the OXTR gene might play a role in the development of impaired social behavior." (PMID 25667571, 2015). "Taking together, we are the first to identify OXTR CpG sites that are significantly dysregulated in PWS subjects and individuals with PWS and psychosis." (PMID 35688807, 2022). "The main finding of the current study was a statistically significant association between rs53576 in OXTR, frequently found to be associated with social behavior in previous studies, and the level of Emotional Withdrawal, a negative symptom frequently occurring in psychotic disorders." (PMID 25667571, 2015). "A recent study reported lower methylation of the OXTR exon region 1 in males with PWS with psychosis compared to those without psychosis." (PMID 37313445, 2023). "We hypothesize that the oxytocin receptor gene is dysregulated in PWS also on an epigenetic level, which could contribute to psychosis in PWS." (PMID 35688807, 2022). "To investigate our hypothesis, we examine the methylation status of CpG sites located at exon 1 and intron 1 of the OXTR gene with a special focus on methylation differences in individuals with PWS and psychosis." (PMID 35688807, 2022). "The authors further found males with PWS and psychosis showed significantly lower methylation of the OXTR exon region 1 than those without psychosis, suggesting that an OT deficiency in PWS might be associated with the higher rate of psychosis found in PWS." (PMID 37313445, 2023). "However, in psychotic disorders the specific contribution of OXTR versus AVPR has not been thoroughly clarified." (PMID 37373400, 2023). "Furthermore, male PWS subjects with psychosis show significantly lower methylation of the OXTR exon 1 region than those without psychosis (p = 0.002)." (PMID 35688807, 2022). "Although the oxytocin system is dysregulated in PWS as well as in ASD and psychosis, two major diseases with high prevalence in PWS, no study to date has examined the epigenetic status of the OXTR gene in PWS and individuals with PWS and psychosis." (PMID 35688807, 2022).
alcohol use disorder (6 papers, 2020 to 2023). "In humans, single nucleotide polymorphisms (SNPs) of the oxytocin receptor (Oxtr) are associated with development of alcohol use disorders (AUD)." (PMID 32666677, 2020). "The present study aims to explore the modulatory role of the polymorphism OXTR rs2254298 on mood disorders during alcohol withdrawal and to help researchers better understand and develop effective relapse prevention and interventions for alcohol use disorders." (PMID 37520225, 2023).
colitis (6 papers, 2019 to 2026). Inflammation of the colon. "Having established that mice with OXTR deficiency in intestinal epithelium exhibit more advanced colitis and colon cancer, we further investigated the role of the OXT system in CAC through OXT supplementation." (PMID 38979515, 2024). "In this study, we observed a significant reduction in the expression of the oxytocin receptor (OXTR) in colon samples from both patient with colitis and patient with CAC." (PMID 38979515, 2024). "To understand the relevance of the decreased expression of OXTR and B3GNT7 in humans, we analyzed an independent cohort of patients with UC and found decreased expression of OXTR in colitis." (PMID 38979515, 2024). "We demonstrate that the depletion of OXTR specifically in IECs contributes to the development of experimental colitis induced by DSS and CAC induced by a combination of DSS and AOM." (PMID 38979515, 2024). "In a mouse models of colitis induced by either dextran sulfate sodium (DSS) or 2,4,6-trinitrobenzene sulfonic acid (TNBS), disease severity was increased in oxytocin receptor (OXTR) deficient mice when compared to wild-type controls." (PMID 35572539, 2022). "In OXTR knockout mice, the intestinal villi and crypts were shorter, intestinal permeability to macromolecules was greater, and experimental colitis was more severe than wild-type mice." (PMID 31920487, 2019). "However, our data unexpectedly reveal a protective role of OXTR in both DSS-induced colitis and AOM/DSS-induced CAC tumorigenesis mouse models." (PMID 38979515, 2024). "Interestingly, we observed a positive correlation between B3GNT7 expression and OXTR expression in human colitis and CAC colon samples." (PMID 38979515, 2024). "Intriguingly, reduced expression of OXTR and B3GNT7 is observed in patients with colitis and CAC, underscoring the clinical relevance of our findings." (PMID 38979515, 2024). "To determine whether AOM or inflammation is necessary for OXTR to suppress CAC, we evaluated a colitis-independent colon cancer model." (PMID 38979515, 2024). "Moreover, our analysis of human colitis and CAC samples reveals down-regulation of OXTR expression, indicating complex and context-dependent roles of OXT signaling under these conditions." (PMID 38979515, 2024).
diabetes (6 papers, 2018 to 2026). "We evaluated the potential effect of OXTR deficiency on maternal diabetes-mediated oxidative stress." (PMID 33633538, 2021). "Our results indicate that prenatal OXTR deficiency potentiates maternal diabetes-mediated oxidative stress." (PMID 33633538, 2021). "We evaluated the potential effect of OXTR deficiency on maternal diabetes-mediated social deficits in male offspring." (PMID 33633538, 2021). "This conclusion has been further supported by the results from our in vivo study, which showed that OXTR expression was suppressed in many brain tissues, including the amygdala, hypothalamus and hippocampus, in prenatal diabetes exposure-induced offspring." (PMID 33633538, 2021). "We evaluated the effect of postnatal expression of ERβ and OXTR on maternal diabetes-mediated social deficits in male offspring." (PMID 33633538, 2021). "In this study, we aim to investigate the potential role of OXTR on maternal diabetes-mediated social deficits." (PMID 33633538, 2021). "In this study, we aim to investigate the potential role of OXTR on maternal diabetes-mediated social deficits in offspring." (PMID 33633538, 2021). "Additionally, postnatal infusion of OXTR partly, while infusion of ERβ completely, reverses maternal diabetes-induced social deficits." (PMID 33633538, 2021). "OXTR knockout mice slightly but significantly mimicked the effect of maternal diabetes in the control (CTL/OXTR–/–) group, while there was no further effect in the diabetic (STZ/OXTR–/–) group." (PMID 33633538, 2021).
endometriosis (6 papers, 2017 to 2023). The growth of functional endometrial tissue in anatomic sites outside the uterine body. "This study also supports an association between the variation in expression of OXTR and endometriosis." (PMID 37443771, 2023). "Of the 210 consensus clusters showing differential expression, 53 promoters passed Bonferroni correction, including genes (IGFBP5, OXTR CALD1) previously associated with endometriosis." (PMID 37443771, 2023). "Consensus clusters associated with genes for oxytocin receptor (OXTR) and pregnancy-specific beta-1-glycoprotein 4 (PSG4) also had lower expression in endometriosis cases in comparison with controls." (PMID 37443771, 2023). "Despite the small sample number, there was evidence of differences associated with endometriosis at 210 consensus clusters, including IGFBP5, CALD1 and OXTR." (PMID 37443771, 2023). "Abnormal oxytocin receptor expression in the JZ in women with endometriosis may lead to abnormal uterine contractility, reduced fertility, and dysmenorrhea associated with endometriosis." (PMID 37886646, 2023). "Moreover, OXTR immunofluorescence staining was also performed in an endometriosis cell line, indicating numerous spots irregularly dispersed in the cytoplasm." (PMID 36835321, 2023). "The abnormal expression pattern of oxytocin receptor in the JZ in women with endometriosis may result in abnormal uterine contractile activity, reduced fertility and dysmenorrhea associated with endometriosis." (PMID 28049501, 2017). "One of the consensus clusters for OXTR was significantly different between women with and without endometriosis." (PMID 37443771, 2023).
alcohol dependence (5 papers, 2022 to 2025). Physical and psychological dependence on alcohol. "The interaction pattern between OXTR rs2254298 and alcohol dependence level fits the weak differential susceptibility model." (PMID 37520225, 2023). "The RoS test and re-parameterized regression analysis indicated that the interaction of OXTR rs2254298 × current environment (alcohol dependence level) fits the weak differential susceptibility model." (PMID 37520225, 2023). "Based on the framework of G × E research on the etiology of alcohol-related mood disorders, we investigated the interaction effect between OXTR rs2254298 and alcohol dependence level on mood disorders in Han Chinese men during alcohol withdrawal." (PMID 37520225, 2023). "We performed a re-parameterized regression analysis to test a specific pattern of alcohol dependence level × OXTR rs2254298." (PMID 37520225, 2023). "In step 3, the interaction of alcohol dependence level and OXTR rs2254298 was included in the regression equation." (PMID 37520225, 2023).
Asperger’s syndrome (5 papers, 2014 to 2025). "OXTR is one of the main molecular pathways that regulate mammalian social behavior, and genetic perturbations in OXTR have been implicated in subpopulations of individuals with asd, including Asperger’s syndrome." (PMID 26273428, 2015). "Previous studies have reported associations between the minor allele of OXTR and ASD, including Asperger syndrome." (PMID 41303266, 2025). "Regarding these functions, perturbations in OXTR have been implicated in subpopulations of individuals with ASD, including Asperger’s syndrome." (PMID 36735095, 2024). "Furthermore, genetic disruptions in OXTR have been linked to certain subpopulations of individuals with ASD, including those with Asperger’s syndrome." (PMID 38474035, 2024).
colon cancer (5 papers, 2019 to 2024). "Among them, GUCA2A, VIP, and OXTR have been demonstrated to be significantly associated with the prognosis of colon cancer." (PMID 35281839, 2022). "Interestingly, prior research utilizing systematic bioinformatics analysis has suggested that high levels of OXTR mRNA are associated with a poor prognosis in colon cancer, implicating OXTR as a potential marker for human colon cancer." (PMID 38979515, 2024). "The present Matrigel invasion study also confirms that OXT significantly inhibits the migration of colon cancer cells, which is mediated by OXTR." (PMID 31920487, 2019). "Importantly, blocking OXTR activation inhibited OXT-induced reduction of colon cancer cell migration in both types of colon cancer cell lines." (PMID 31920487, 2019). "Moreover, cell invasion experiment showed that OXT treatment reduced the invasion ability of colon cancer cells and blocking OXTR with atosiban blocked OXT-reduced invasion ability of human colon cancer cell lines Ls174T and SW480." (PMID 31920487, 2019). "Furthermore, the effects of the IRGs on colon cancer development remain unclear, although cancer progression has been linked to CD1B, XCL1, PLCG1, NGF, and OXTR." (PMID 32508884, 2020). "Additionally, using Transwell migration assay, we observed effects of OXT with and without OXTR antagonist on the migration of colon cancer cells." (PMID 31920487, 2019).
mood disorder (5 papers, 2011 to 2024). A cognitive disorder a disturbance in which the person's mood is hypothesized to be the main underlying feature. "Specifically, genes, such as NR3C1, SLC6A4, BDNF, FKBP5, SKA2, and OXTR, exhibit alterations in DNA methylation patterns that are frequently linked to mood disorders." (PMID 38792892, 2024). "OXTR binds to its endogenous nonapeptide ligand oxytocin that is associated with several social behaviors and emotional regulation as well as to mood disorders." (PMID 35361281, 2022).
social anxiety disorder (5 papers, 2017 to 2024). "A recent study of patients with social anxiety disorder (SAD) reported that SAD is associated with increased oxytocin receptor (OXTR) gene high methylation." (PMID 36032246, 2022). "On the other hand, hypomethylation in promoter of OXTR (oxytocin receptor) is a risk factor for increasing amygdala activity towards social anxiety-related words in social anxiety disorder diagnosis (SAD) and increasing cortisol release during the Trier Social Stress Test (TSST)." (PMID 33049717, 2020). "One recent study conducted in social anxiety disorder (SAD) patients reported an association between SAD and oxytocin receptor (OXTR) gene hypomethylation." (PMID 28149334, 2017).
alexithymia (4 papers, 2015 to 2024). An agnosia that is a deficiency in understanding, processing, or describing emotions. "They tested potential associations between oxytocin receptor gene single nucleotide polymorphisms or haplotypes and alexithymia in 355 patients with obsessive-compulsive disorder." (PMID 36699481, 2022). "Several neuroimaging studies suggested that the genetic variants of OXTR modulate the activities of limbic circuits including the amygdala, the hypothalamus, and the cingulate gyrus, which are also associated with alexithymia." (PMID 26599592, 2015). "Lastly, while our sample size was relatively larger than those in previous studies examining associations between OXTR SNPs and alexithymia-related conditions, our power is still limited." (PMID 26599592, 2015). "However, not all of the studies consistently reported a positive association between OXTR variants and alexithymia-related traits." (PMID 26599592, 2015). "Therefore, it would be necessary to evaluate the effects of OXTR variants on alexithymia with particular consideration towards those confounding factors and limitations." (PMID 26599592, 2015). "Hence, we sought to investigate the association between OXTR genetic variants and alexithymia in patients with OCD, who supposedly have more variability in alexithymic traits than controls." (PMID 26599592, 2015). "Finally, for the OXTR gene, one candidate variant for alexithymia risk is the rs53576 polymorphism." (PMID 39202385, 2024). "Thus, elucidating the relationship between the OXTR gene and alexithymia may help identify predisposing genes for OCD." (PMID 26599592, 2015). "Therefore, oxytocin receptor gene polymorphisms may contribute to individual differences in alexithymia, which is considered to be a dysfunction of emotional processing." (PMID 26599592, 2015). "The main candidate genes associated with alexithymia are from the serotoninergic pathway (SLC6A4, HTR1A and HTR2A) and neurotransmitter metabolism (DRD2/ANKK1, COMT, BDNF, and OXTR)." (PMID 39202385, 2024). "Further, there is evidence for a gene-environment interaction contributing to alexithymia, with variation in the oxytocin receptor gene and insecure childhood attachment contributing to high alexithymia levels." (PMID 36699481, 2022). "Machine learning and unbiased cluster analyses could be performed in healthy individuals and in various disorders to test, for example, links between alexithymia and variations in cortisol and oxytocin receptor genes." (PMID 36699481, 2022). "Studying the effect of the OXTR gene on alexithymia in OCD has several advantages." (PMID 26599592, 2015). "OXTR SNPs have some influence on structural and functional changes in several brain regions involved in processing social-emotional information such as the prefrontal cortex, anterior cingulate cortex, amygdala, and hypothalamus, all of which are also important in the pathophysiology of alexithymia." (PMID 26599592, 2015).
behavioral disorder (4 papers, 2009 to 2023). "A reduction was seen in oxytocin receptor (OXTR) expression which has been linked to behavioural disorders and prolonged labour." (PMID 37363400, 2023). "There are now numerous studies which conclude that polymorphisms in the OXTR gene confer a risk of behavioural disorders." (PMID 37363400, 2023). "The connection between ALDH1A1 and ALDH3A1 loss and corneal opacities, and OXTR loss and prolonged labour and behavioural disorders provides a new explanation for the extracutaneous features of RXLI." (PMID 37363400, 2023). "There is evidence that ALDH1A1 and ALDH3A1 are important for transparency of the cornea, whereas OXTR has been linked to behavioural disorders and is known to regulate parturition." (PMID 37363400, 2023). "In addition, there was significant downregulation of aldehyde dehydrogenase family members and the oxytocin receptor which have been linked to corneal transparency and behavioural disorders respectively, both of which are extracutaneous phenotypes of RXLI." (PMID 37363400, 2023). "Previous studies have found that maternal oxytocin level may be determined by CD38 and oxytocin receptor gene polymorphisms (e.g., OXTR rs53576), which are associated with child behavior problems." (PMID 32581866, 2020).
colorectal cancer (4 papers, 2019 to 2024). A primary or metastatic malignant neoplasm that affects the colon or rectum. "However, the effect of OXTR signaling on the development of colorectal cancer (CRC) and its underlying mechanisms remain unexplored." (PMID 31920487, 2019). "Moreover, OXTR level was positively associated with colorectal cancer." (PMID 34877409, 2021). "Colorectal cancer development is associated with the reduction of OXTR signaling since OXT can suppress FAPα and CCL-2 expressions and their associated CAC migration via OXTR." (PMID 31920487, 2019).
Headache (4 papers, 2020 to 2024). Cephalgia, or pain sensed in various parts of the head, not confined to the area of distribution of any nerve. "Background and Purpose: The intranasal administration of oxytocin (OT) reduces migraine headaches through activation of the oxytocin receptor (OTR)." (PMID 35631690, 2022).
hemorrhage (4 papers, 2021 to 2023). Loss of blood from the vascular compartment to the exterior or into nonvascular body space as a result of rupture or severance of the blood vessels. "Those with higher OXTR DNA methylation required more oxytocin during parturition and had a higher risk of postpartum hemorrhage." (PMID 36707542, 2023). "Considering that postpartum hemorrhage is commonly attributed to uterine atony, reduced availability of OXTR might associate with greater postpartum hemorrhage risk." (PMID 36707542, 2023). "Next, we tested for OXTR DNA methylation differences in blood between individuals who experienced a postpartum hemorrhage arising from uterine atony and matched controls following vaginal birth." (PMID 36707542, 2023).